C18orf32 (chromosome 18 open reading frame 32)
Description:
May activate the NF-kappa-B signaling pathway.
Synonyms: FLJ23458; GPIBD25
Tractability: PROTAC: ubiquitination databases record sites on it; its protein half-life has been measured.
Gene: Protein-coding gene on chromosome 18 (49,477,243 to 49,487,256, reverse strand). Ensembl gene ENSG00000177576.
Subcellular location: Endoplasmic reticulum; Lipid droplet
Subcellular location (Human Protein Atlas): Vesicles; Nucleoplasm
Gene Ontology:
Molecular function: protein binding
Biological process: positive regulation of canonical NF-kappaB signal transduction
Cellular component: endoplasmic reticulum; lipid droplet
Genetic constraint (gnomAD): Loss-of-function variants: 4 observed, 5.65 expected, observed/expected ratio (o/e) 0.71, 90% interval 0.35 to 1.56. That is too few expected variants to judge how well the gene tolerates losing a copy. Missense variants: 67 observed, 70.62 expected, observed/expected ratio (o/e) 0.95, 90% interval 0.78 to 1.16. Synonymous variants: 23 observed, 23.47 expected, observed/expected ratio (o/e) 0.98, 90% interval 0.7 to 1.39.
Homologues: Orthologues: chimpanzee C18H18orf32 (96% identical), pig C18orf32 (84% identical), guinea pig C18orf32 (82% identical), dog C18orf32 (80% identical), mouse BC031181 (76% identical), rat C18h18orf32 (72% identical), tropical clawed frog c1h18orf32 (53% identical).
Diseases named in the same sentence as C18orf32 in open-access papers:
C18orf32 is named in the same sentence as 4 diseases in open-access papers, as found by Europe PMC text mining. Sharing a sentence is not in itself a finding about the gene and the disease.
C18orf32 shares sentences with these, for which no sentence is quoted: gastric cancer (1 paper); intellectual impairment (1); stomach adenocarcinoma (1); tumor (1).